BCL2 (BCL2 apoptosis regulator)
Diseases named in the same sentence as BCL2 in open-access papers (continued):
Sharing a sentence is not in itself a finding about the gene and the disease.
leukemia (continued). "Therefore, we analysed primary and secondary Fli-1 leukaemias and MigR1 controls for Bcl-2, Bcl-xL and Mcl-1 mRNA expression by Q-PCR." (PMID 23667468, 2013). "In addition, HS-1793 was also demonstrated to circumvent Bcl-2-mediated apoptosis resistance in leukemia cells." (PMID 23483560, 2013). "To identify combinations of compounds that synergistically inhibit the growth of human leukemia cells we performed a small molecule screen by combining the BCL2 inhibitor, ABT-737 with 1280 drugs in the library of pharmacologically active compounds (LOPAC1280)." (PMID 23342165, 2013). "Importantly, honokiol-induced CyP-D-regulated cell death was shown to be able to overcome Bcl-2 and Bcl-XL-mediated apoptotic resistance in primary human leukemia cells." (PMID 23483560, 2013). "Importantly, MJ-29-stimulated CDK1 activation appears to be acting the phosphorylation of Bcl-2 (Ser70), resulting in promotion of the intrinsic apoptotic signaling in human leukemia U937 cells." (PMID 22662126, 2012). "High levels of BCL2 have potential oncogenic effects in a conditional BCL2 transgenic mouse and may contribute to the pathogenesis of leukemia." (PMID 24213472, 2012). "The increase in anti-apoptotic Bcl-2 protein may serve as a compensatory protection of the leukemia cells upon Hemidesmus insult." (PMID 21738701, 2011). "We therefore conclude that ponicidin has significant anti-proliferation effects by inducing apoptosis on leukemia cells in vitro, downregulation of survivin as well as Bcl-2 expressions may be the important apoptosis inducing mechanisms." (PMID 19330074, 2008). "Ponicidin has significant anti-proliferation effects by inducing apoptosis on leukemia cells in vitro, downregulation of survivin as well as Bcl-2 expressions may be the important apoptotic inducing mechanisms." (PMID 19330074, 2008). "Moreover, we observed that Smurf2 knockdown increased the expression of Bcl-2 in leukemia cells." (PMID 40978141, 2025). "Notably, Smurf2 upregulation inhibited the expression of Bcl-2 in leukemia cells." (PMID 40978141, 2025). "Also, low expression of the BCL2 gene may lead to better OS and leukemia-free survival (LFS) in patients undergoing allo-HSCT." (PMID 39048974, 2024). "Importantly, this increased high metabolic activity in VEN-resistant cells can serve as a target for therapeutic intervention and co-targeting of BCL-2 and OxPhos showed synergistic anti-leukemia activity, thus providing a basis for further preclinical and potential clinical evaluation." (PMID 38961053, 2024). "Thus, combined treatment with IMPDH and BCL2 inhibitors could be promising frontline therapies for MLL‐fusion leukemia." (PMID 36453131, 2023). "The data from the current study provide partial but important evidence that polymorphisms in apoptotic genes Bcl-2-938C>A and Bax-248G>A and pro-inflammatory cytokines IL-8 rs4073 T>A and TNF-α rs1800629 G>A may help predict the clinical outcomes of patients with leukemia." (PMID 37232720, 2023). "Likewise, overexpression of FTO could promote BCL-2 expression, thereby reducing the sensitivity of leukemia cells to tyrosine kinase inhibitors (TKIs)." (PMID 35843942, 2022). "Since MEF2C is normally downregulated during the ETP stage, prolonged or enhanced MEF2C expression may cause supraphysiological IL-7R signaling and BCL2 expression that contributes to the arrest, survival, and enhanced growth of ETP cells resulting in leukemia." (PMID 35536646, 2022). "Similarly, activation of BCL2 is observed in MLL-rearranged leukemia patients." (PMID 34210001, 2021). "Relative to other hematological malignancies, CLL is a non-proliferative form of leukemia associated with constitutive activation of the B-cell receptor signaling pathway and overexpression of the B-cell lymphoma 2 (BCL-2) family of anti-apoptotic proteins (e.g., BCL-2, MCL-1)." (PMID 34041038, 2021).
leukemia (continued). "Other studies of anticancer effects of DMC on different cancer cell lines (K562 (leukemia cells) or PANC-1 (pancreatic cancer cells)) also indicated that the chalcone could lower Bcl-2/Bax ratio by decreasing the expression of Bcl-2 gene and activating caspase-3 and caspase-9." (PMID 33204293, 2020). "RPL10R98S mutant leukemia cells may increase the expression of anti-apoptotic protein BCL2." (PMID 32185137, 2020). "Finally, RPL10R98S mutant leukemia cells are potentially sensitive to Bcl2 inhibitor venetoclax." (PMID 32185137, 2020). "Recently, it has been reported that targeting Bcl2 is not effective as monotherapy for the treatment of childhood leukemia, but it becomes effective when associated with other drugs, such as inhibitors of survival pathways, thus allowing to induce apoptosis and to reduce side effects." (PMID 33255367, 2020). "Moreover, the upregulation in the expression of anti-apoptotic protein BCL2 in this study could suggest that ENU induced leukaemia in mice model through evading apoptosis." (PMID 32183192, 2020). "In addition, the extract of red ginseng could inhibit cell proliferation and induce apoptosis by activating caspase-3, downregulating antiapoptotic Bcl-2 and Bcl-X(L), and decreasing telomerase activity in human leukemia U937 cells." (PMID 31354479, 2019). "Additional studies also showed that oridonin could inhibit cell growth and induce apoptosis in cervical cancer HeLa, gallbladder cancer SGC996 and NOZ, and leukemia K562 cells via alteration of the Bcl-2/Bax ratio with decreased expression of Bcl-2 and increased expression of Bax in mitochondria." (PMID 31354479, 2019). "In addition, frequent dysregulation of prosurvival pathways such as BCL-2, which counteracts the intrinsic mitochondria-mediated apoptotic pathway, may contribute to the therapeutic difficulties many of these leukemias pose in the clinical setting." (PMID 28232907, 2017). "In general, several other genes, such as BCL2 have previously been described to be important for MLL-r tumour cell development or survival in such a way that suppression of gene expression is able to abolish MLL-r leukemia by proliferation arrest and/or apoptosis induction." (PMID 27317766, 2016). "Thus, CAUE may be an effective chemotherapy for leukemia, and decreases in Bcl-2 expression via co-treatment with other chemotherapeutical reagent may enhance the chemotherapeutic action of CAUE on leukemia patients." (PMID 23229564, 2013). "Similarly, butein increased Bax expression and decreased Bcl-2 expression in HL60 leukemia cells." (PMID 22245810, 2012). "Notably, we found that bufalin induced apoptosis is associated with the downregulation of Bcl-2 expression and upregulation of Bax expression in A549 cells, consistent with previous report that overexpression of Bcl-2 protein inhibited bufalin-induced apoptosis of leukemia cells." (PMID 22408435, 2012). "In a zebra fish model of human NOTCH1-induced T-cell leukemia, the leukemia onset was dramatically accelerated when the transgenic fish was crossed with another line over expressing the zebra fish Bcl2 gene, indicating synergy between the Notch pathway and the Bcl2-mediated antiapoptotic pathway." (PMID 23021489, 2012). "However, some of the diatom extracts were able to kill also leukemia cells overexpressing Bcl-2." (PMID 20098602, 2009). "For instance, the approval of venetoclax, an inhibitor of BCL2-BAX interaction, to treat leukemia, provides tangible evidence of the therapeutic potential of targeting PPIs." (PMID 41550490, 2026). "This action facilitates leukemia stem cell self-renewal, accelerates AML progression, and influences the sensitivity to the BCL2 inhibitor Venetoclax." (PMID 40806675, 2025). "Meanwhile, a study on leukemia cells found that treating them with TGF-β promoted cell death, increased Bax, and decreased Bcl-2 expression." (PMID 39858257, 2025).
leukemia (continued). "By enhancing the expression of anti-apoptotic proteins such as BCL-2 and MCL-1, JAK-STAT signaling can help leukemia cells resist the cytotoxic effects of chemotherapy." (PMID 40486651, 2025). "The upregulation of anti-apoptotic proteins, such as BCL-2 and MCL-1, in response to JAK-STAT activation, can make leukemia cells more resistant to the pro-apoptotic effects of chemotherapeutic agents." (PMID 40486651, 2025). "A variety of other kinase inhibitors are used or in trials for hematologic cancers (e.g. PI3K inhibitors like idelalisib, BCL2 inhibitor venetoclax, MEK inhibitors in trials for certain leukemias)." (PMID 41568391, 2025). "Hence, our results indicate that cellular differentiation is a targetable state in pedAML and suggest that selective chemotherapy may improve outcome in more differentiated leukemias and that targeted treatments with BCL2 or HDAC inhibition may improve outcome in more HSC-like leukemias." (PMID 40840446, 2025). "Its downstream targets include anti-apoptotic proteins such as Bcl-2, and MDK also facilitates drug efflux by upregulating ABC transporters, such as MDR1 and ABCG2, leading to multidrug resistance in gastric, leukemia, and ovarian cancer models." (PMID 40500394, 2025). "METTL14 causes the occurrence and development of leukemia by modifying MYB/MYC-targeted genes with m6A RNA, and m6A promotes the translation of c-MYC, BCL2, and PTEN in leukemia patients." (PMID 38970366, 2024). "In leukemia THP-1 cells, β-elemene promotes dissociation of Bcl-2/Beclin-1 complex, leading to autophagosome generation and cell autophagy." (PMID 38879549, 2024). "Conversely, other findings indicate that MSC-derived EVs can induce apoptosis in leukemia cells by altering the expression of pro-apoptotic proteins like BID and BAX while decreasing the expression of anti-apoptotic proteins like BCL2." (PMID 39572459, 2024). "BMPR2i synergistically induced cell death when combined with BCL-2 inhibitors or microtubule targeting agents in both NSLC and leukemia cells." (PMID 39315260, 2024). "I-BET 151 induced G1 phase cell-cycle arrest and apoptosis for mixed lineage leukemia (MLL), achieved by reducing the binding of BRD4 to the promoter regions of MYC, BCL2, and CDK6." (PMID 38539460, 2024). "MYBMIM led to MYB-p300 dissociation, suppression of MYB activity followed by downregulation of MYC and BCL2, apoptosis induction in AML cells, and prolonged survival in patient-derived MLL-rearranged leukemia mouse model." (PMID 38835346, 2024). "The expression of c-Myb (a DNA-binding transcription factor) leads to the growth of leukemia by cyclin D3, CDK6, and Bcl-2." (PMID 39598723, 2024). "The expression of proteins related to apoptosis and autophagy, including cleaved-PARP-1, Bcl-2, Bax, LC3-I/II, Beclin-1, Atg5, p62, phospho-AMPK, AMPK, phospho-mTOR, mTOR, phospho-Akt, and Akt, in human leukemia cells were evaluated using Western blotting." (PMID 36826047, 2023). "Activation of STAT5 promotes cell survival through a Bcl-2-independent mechanism, instead of activating Bcl-2, STAT5 can activate the PI3K/AKT/mTOR intracellular signaling pathway and leads to leukemia progression." (PMID 37345151, 2023). "A study published in 2022 showed that CDK7 inhibitors suppressed both leukemia stem cell (LSC)-enriched subsets in vivo and synergized with the BCL-2 inhibitor venetoclax." (PMID 36982970, 2023). "In leukemia cells, studies have found a corresponding regulatory relationship between RUNX1 and BCL2, in which BCL2 as an essential regulator participates in the dual function of RUNX1 on survival." (PMID 37760803, 2023). "The dysregulation of the MAPK–ERK signalling pathway is involved in the malignant transformation of several cancers, including leukaemia with ERK‐mediated increase in anti‐apoptotic proteins, BCL‐2, and BCL‐XL is contributing to disease progression." (PMID 36478132, 2023).
leukemia (continued). "To confirm the role of the JAK-STAT3 pathway, we treated leukemia cell lines with sorafenib and Stattic, a STAT3 inhibitor, and detected the BCL2 expression using Western blot." (PMID 37887047, 2023). "Directly targeting this reciprocity by combined BCL-2 and MCL-1 inhibition showed efficient anti-leukemia activity, providing strong evidence for further evaluation of this combinatorial approach." (PMID 35031695, 2022). "The human leukemia MOLT-3 cells and the cell line overexpressing Bcl-2 (U-937/Bcl-2) were also sensitive to these hybrid compounds." (PMID 36555165, 2022). "Further research can concentrate on the expression of genes and proteins (mainly Bcl-2 and EFGR), evaluation of the effects of T1m on leukemia stem cells, determination of its in vivo bioavailability, and finally, toxicity studies." (PMID 36500355, 2022). "It was cytotoxic against leukemia cells (U-937, HL-60, MOLT-3, and NALM-6) with significant effects against Bcl-2-overexpressing U-937/Bcl-2 cells as well as the human melanoma SK-MEL-1 cell line." (PMID 36555165, 2022). "In that regard, TR was able to promote cell death even in myeloid leukemia cells overexpressing BCL-2 and BCL-xL, which is interesting considering that overexpression of antiapoptotic proteins is a resistance mechanism in leukemia treatment." (PMID 36294912, 2022). "The utility of restoring apoptosis in cancer cells through inhibition of pro-survival BCL-2 proteins has been realized in the clinic, where the first specific inhibitor of BCL-2 is approved for use in leukemia." (PMID 35349392, 2022). "The effect of combining BCL-2 and MCL-1 inhibition by venetoclax and S63845 was evaluated in vivo and strongly enhanced anti-leukemia activity was found in a pre-clinical patient-derived xenograft model." (PMID 35031695, 2022). "The promise of targeting apoptotic pathways as a feasible therapeutic strategy in leukemia has been recently demonstrated by the approval of venetoclax, a BH3-mimetic to inhibit the antiapoptotic molecule Bcl-2." (PMID 35463978, 2022). "When apigenin was used in combination with etoposide, there was a synergistic decrease of BCL2 gene expression in both myeloid (THP-1) and lymphoid (Jurkat) leukaemia cells compared to both apigenin alone and etoposide treatment alone." (PMID 35614109, 2022). "Treatment with venetoclax, a Bcl-2-specific inhibitor and FDA-approved leukemia therapy drug, also markedly promoted the enucleation of hCB-MNC-derived erythroblasts." (PMID 36270980, 2022). "In the case of MLL fusion-mediated leukemia, MLL fusion proteins directly activate both MYC and HOXA9, while HOXA9 maintains expression of MYC, BCL2, and SOX4, achieving high MYC activity and anti-apoptotic properties simultaneously." (PMID 34310280, 2021). "METTL3, the main m6A methyltransferase, inhibits cell differentiation and apoptosis and promotes cell proliferation by increasing the translation of c-myc, bcl-2 and PTEN in leukemia." (PMID 33658391, 2021). "Oppositely, FTO upregulation in leukemia showed more TKI tolerance via enhancing MERTK and BCL-2 stability." (PMID 34745970, 2021). "Aberrant Bcl-2 overexpression is identified in patients with AML, rendering survival advantage for the leukemia cells." (PMID 35155192, 2021). "KMT2Ar leukemias, as well as MYC-driven B cell lymphomas, are highly sensitive to inhibition of BCL2 through venetoclax treatment." (PMID 34088716, 2021). "Based on information gained by computational structure modelling, the authors develop a PROTAC that induces degradation of both BCL-xL and BCL-2 and effectively targets BCL-xL/2-dependent leukaemia cells." (PMID 34824248, 2021). "MCL-1 has been recognized as the major critical protein accounting for the resistance of leukemia cells against FDA-approved BH3 mimetic drugs, such as ABT-737 that antagonizes BCL-2, BCL-xL, or BCL-w and venetoclax (ABT-199, the BCL-2 specific inhibitor)." (PMID 34294680, 2021).
leukemia (continued). "We investigated the combination of FLT3 TKIs (Gilteritinib or Sorafenib), with Venetoclax, a BCL-2 selective inhibitor (BCL-2i), on FLT3/ITD leukemia cells." (PMID 34024909, 2021). "BCL2 was highly expressed in MLL fusion-mediated leukemia, and many human MLL fusion leukemia cell lines were sensitive to a BCL-2 inhibitor (i.e. ABT-199)." (PMID 34310280, 2021). "Next, we examined the roles for endogenous BCL2 and SOX4 in maintaining leukemia-initiating cells using a mouse leukemia cell line that we previously established with MLL-ENL." (PMID 34310280, 2021). "Other key factors important for leukemia survival include MYC and BCL2, particularly in relation to venetoclax treatment." (PMID 34088716, 2021). "Some of them, such as hypomethylating agents, FLT3 and Bcl-2 inhibitors, have been used in combination with DLI, aiming to enhance the graft-versus-leukemia effect." (PMID 35155192, 2021). "Hydrazostat enhances the sensitivity of NB and leukemia cells to RTK inhibitor imatinib, cytotoxic drugs cytarabine and vincristine and BCL2 inhibitor venetoclax." (PMID 34944663, 2021). "Among these, the combined treatment of BCL-2 and PI3K inhibition enhanced leukemia cell death in AML cell lines, patient-derived blasts and xenograft models." (PMID 34109125, 2021). "have reported that both Bcl-2 and CCNE1 were positively regulated by NUDT21 and they mediated the promoting role of NUDT21 in human leukemia cells." (PMID 34660260, 2021). "Our data indicated that kaempferol compared to EGCG, further inhibited cell growth and induced apoptosis in leukemia HL60 cells by inhibiting MDR and increasing Bax/Bcl2." (PMID 34290963, 2021). "Because there is a correlation between the expression levels of HOX proteins and the sensitivity to BCL2 inhibitor in AML patient samples, the aberrant expression of HOXA9 is the potential mechanism for BCL2-dependence of MLL leukemia." (PMID 34310280, 2021). "Human leukemia cell line RS4;11 which is dependent on BCL-2 for survival was more sensitive to Maritoclax treatment compared to HeLa cells which are dependent on MCL-1 for survival." (PMID 33214852, 2020). "The BCL-2 inhibitor ABT-199, in clinical trials for leukemia, was also shown to reduce the level of airway eosinophils and Th2 cells in a mouse model of asthma." (PMID 33076829, 2020). "METTL3 was up-regulated in acute myeloid leukemia cells, enhanced translation of c-MYC, BCL2, and PTEN mRNAs, blocks cell differentiation and apoptosis, and promotes leukemia progression." (PMID 33363011, 2020). "Studies of leukemia cell line sensitivity identify mixed lineage leukemia (MLL) gene status and the level of B-cell lymphoma 2 (BCL2) family proteins as potential markers for selection of patients with greater sensitivity to fadraciclib." (PMID 32645016, 2020). "In the meantime, studies on leukemia indicated that m6A modification promotes the translation of oncogenes c-MYC, Bcl-2, and PTEN." (PMID 33061938, 2020). "Compound 3 stimulated leukemia cell programmed cell death, confirmed by the stimulation of caspase-3, degradation of PARP, increase of Bax, and reduction of Bcl-xl and Bcl-2." (PMID 33375664, 2020). "Among these molecules, BCL-2 was found over-expressed in breast CSCs, while both BCL-2 and BCL-xL were found up-regulated in leukemia CSCs." (PMID 30834247, 2019). "Mitochondrial uncoupling by BCL-2 inhibitors BH3I-2′ and HA14-1 was synergistic with TRAIL-induced apoptosis in leukemia cells." (PMID 31409768, 2019). "In MLL-AF9 leukemia models overexpressing BCL-2 and MCL-1 it was provided evidence that the combination of BCL-2 and MCL-1 inhibitors resulted in a synergistic anti-leukemic effect, when used alone or in combination with standard anti-leukemic drugs." (PMID 30813354, 2019). "Namely, CD34 positive cells present a greater BCL-2 level compared to CD4+ CD8+ cells, suggesting that more undifferentiated T-ALL leukemia cells express greater levels of BCL-2." (PMID 31226848, 2019).